ACAN (aggrecan)
Diseases named in the same sentence as ACAN in open-access papers (continued):
Sharing a sentence is not in itself a finding about the gene and the disease.
Arthritis (continued). "Levels of aggrecan ARGS fragments in human synovial fluid are increased in human arthritis, OA and after knee injury, likely reflecting an enhanced cleavage at the 392Glu-393Ala bond in the IGD by aggrecanase." (PMID 19545413, 2009). "This time lag between changes in aggrecan and collagen II markers in SF coincides with that seen in cartilage extracts in the rat mono-iodoacetate model of arthritis." (PMID 19272138, 2009). "Aggrecanase cleavage at the 392Glu-393Ala bond in the interglobular domain (IGD) of aggrecan, releasing N-terminal 393ARGS fragments, is an early key event in arthritis and joint injuries." (PMID 19545413, 2009). "Of most interest is the recent discovery of a group of enzymes of the ADAMTS family named aggrecanases, which cleave the aggrecan core protein and are believed to play a determinant role in arthritis in the breakdown of aggrecan." (PMID 16207326, 2005). "According to the OA meniscus destabilization model, several researchers found that protecting mice’s joints against degeneration involved active ADAMTS-5 (aggrecanase 2), indicating that the ADAMTS-5-mediated breakdown of aggrecan is critical for the onset of arthritis." (PMID 37259405, 2023). "In arthritis, there is enhanced production and activation of aggrecan-degrading enzyme disintegrin, metalloproteinase with thrombospondin motif (ADAMTSs) and matrix metalloproteinases (MMPs) resulting in degradation of aggrecan and type II collagen of articular cartilage, respectively." (PMID 36282841, 2022). "This suggested the possibility that ECM-bound or cell surface-bound ADAMTS4 may be mobilized through autocatalysis, which now allows ADAMTS4 to reach its substrate aggrecan and contribute to its degradation in cartilage resulting in arthritis." (PMID 34268335, 2021). "The development of inhibitors for ADAMTS proteases is primarily focused on inhibiting ADAMTS4 and ADAMTS5 due to their prominent role in cartilage destruction in arthritis where both proteases degrade aggrecan, a major structural proteoglycan in the articular cartilage." (PMID 34268335, 2021). "Additionally, since aggrecan is present in cartilaginous tissue, cartilaginous pathology (early-onset arthritis and intervertebral disc disease) has been observed." (PMID 32939436, 2020). "Along with aggrecan breakdown, degradation of collagen is a central feature of arthritis." (PMID 30691120, 2019). "Both ADAMTS4 and ADAMTS5 are responsible for aggrecan degradation in a human model of arthritis." (PMID 29757957, 2018). "In cartilage, the principal matrix proteoglycan is aggrecan, the protease-mediated catabolism of which defines arthritis; however, the pathophysiologic mechanisms that drive aberrant aggrecanolytic activity remain unclear." (PMID 29920219, 2018). "In the early stages of arthritis, aggrecan removal precedes collagen degradation in cartilage." (PMID 28270508, 2017). "The in vitro data obtained in this study shows that chondrocytes treated with celecoxib produce fewer arthritis-associated mediators such as PGE2 and MMP-1 than chondrocytes treated with piroxicam or prednisone and more anabolic indicators, namely, CII and aggrecan." (PMID 26000299, 2015). "Furthermore, Timp-3 knockout mice present with an increased inflammatory response to antigen-induced arthritis and increased aggrecan and collagen II degradation with age." (PMID 25606593, 2014). "Using an adoptive transfer system, p135H peptide-stimulated lymphocytes and T cell hybridomas from peptide p135H-primed BALB/c mice were also capable of inducing arthritis in SCID mice “presensitized” with a single injection of PG aggrecan, with a relatively high incidence and severity score." (PMID 24605340, 2014). "Knockdown of Adamts9 expression using lentiviral shRNA in 3D chondrocyte culture resulted in an increase in matrix deposition and decrease in aggrecan degradation, suggesting an importance of Adamts9 in cartilage breakdown during pathological conditions such as arthritis." (PMID 24213506, 2012).
Arthritis (continued). "In summary, these data appear to mimic cartilage degradation in arthritis where aggrecanase activity on aggrecan precedes MMP mediated aggrecan degradation that is subsequently followed by MMP degradation of collagen, which has been reported with various techniques from other labs." (PMID 18513402, 2008). "This alone could explain the differences in the arthritis, since it has been shown in several earlier studies that the serum antibody levels against the proteoglycan aggrecan (and its immunodominant region: G1 domain) and CCP show the strongest correlation with the severity of GIA." (PMID 32859051, 2020). "However, whether ADAMTS4 or ADAMTS5 is predominately responsible for the cleavage of aggrecan in arthritis in humans remains controversial." (PMID 25606593, 2014). "Current data support the hypothesis that aggrecanases are active early in the disease process, with later increases in MMP activity (several MMPs can also degrade aggrecan), but the exact enzyme(s) responsible for cartilage aggrecan destruction at any stage in arthritis is unclear." (PMID 15899037, 2005). "Col2a1 and aggrecan are the main components of ECM, and their destruction plays a crucial role in the onset and progression of early arthritis." (PMID 40746264, 2025). "The analysis revealed a reduced distribution and expression of aggrecan and COL2 genes in the cartilage tissues of arthritis patients." (PMID 39990652, 2025). "In the ERN1 cKO ACLT mouse model, more severe loss of proteoglycan in safranin O staining, a significantly higher arthritis score, elevated expression of MMP13 and ADAMTS5, and reduced expression of aggrecan and Col2 were observed." (PMID 37907740, 2023). "Furthermore, a recent study revealed that ADAMTS-5 also cleaves inter-α-inhibitor and releases active heavy chain 2, which is detectable in synovial fluids from both RA and OA patients, and may contribute to the progression of arthritis beyond the degradation of aggrecan." (PMID 32772139, 2021). "Therefore, miR-3074-5p is a critical mediator in controlling aggrecan and COL2 production during arthritis." (PMID 39990652, 2025). "The primary symptom of early arthritis is believed to be a decline in ACAN According to our findings, PN prevented the breakdown of the ECM by stopping the deterioration of COL2A1 and ACAN." (PMID 37569659, 2023). "On the other hand, ADAMTS proteases are also involved in the pathogenesis of acquired and congenital connective tissue disorders, most prominently in arthritis, where ADAMTS4 and ADAMTS5 degrade aggrecan and contribute to the erosion of articular cartilage and joint degeneration." (PMID 34268335, 2021). "Thiazolidinediones failed to prevent cartilage lesions and arthritis-induced inhibition of proteoglycan synthesis, aggrecan mRNA level or glycosaminoglycan content in patellar cartilage, but reduced bone erosions and inflammatory bone loss." (PMID 18199331, 2008). "To enhance our understanding of the roles of aggrecan and COL2 in arthritis, we analysed the publicly available single-cell RNA sequencing dataset (GSE55460), comprising samples from normal human cartilage tissues and cartilage tissues from patients with arthritis." (PMID 39990652, 2025). "Therefore, an ideal small molecule or biologic inhibitor for ADAMTS5 as a disease modifying arthritis drug would be, one, highly specific for ADAMTS5; two, spare substrates other than aggrecan; and, three, deliverable to or become selectively activated in articular cartilage or the synovium." (PMID 34268335, 2021). "The activity of proteases, including the aggrecan proteoglycan-degrading aggrecanases, members of the a disintegrin and metalloproteinase with thrombospondin motifs (ADAMTS) family and collagenase members of the matrix metalloproteinase (MMP) family, are highly significant in arthritis." (PMID 29920219, 2018).
Arthritis (continued). "Aggrecan degradation facilitated by MMP and ADAMTS enzymes is a process that occurs within normal and arthritic cartilage, signifying a role for these proteases in normal turnover as well as in arthritis, whereas structural changes in aggrecan occur during healthy aging." (PMID 25606593, 2014). "Studies with Adamts4-null mice disclosed that these mice were phenotypically normal and showed no protection against aggrecan degradation in inflammatory or surgically induced arthritis in mice, indicating that ADAMTS4 is not the main aggrecanase in mouse arthritis." (PMID 24213506, 2012).
disc degeneration (44 papers, 2009 to 2025). "Deletion of Sox9 in Aggrecan‐expressing IVD tissues affects disc degeneration and associated pain behaviors through the β–catenin–CCL2 pathway." (PMID 40012719, 2025). "It has been reported that a variant of ACAN (c.4634delT, Leu1545Profs*11) is associated with short stature and intervertebral disc disease." (PMID 39905544, 2025). "The degradation and loss of aggrecan result in impairment of disc function and the onset of disc degeneration." (PMID 33706752, 2021). "Fewer and shortened CS chains can impair the ability of aggrecan to aggregate with HA, and cause further fragmentation of the PG, leading to the disc degeneration." (PMID 33543030, 2020). "Our report provides further evidence that ACAN mutations are associated with autosomal dominant short stature with intervertebral disc disease." (PMID 33298914, 2020). "The increased fragmentation and loss of proteoglycan, specifically aggrecan, are hallmarks of disc degeneration." (PMID 30900385, 2019). "Aggrecan gene VNTR polymorphism had an association with degeneration of lumbar intervertebral discs that the shorter VNTR repeats increasing the chance of the disc degeneration in this population in the North of Iran." (PMID 35919638, 2022). "Aggrecan loss is an early event in disc degeneration, although it is a lengthy process." (PMID 33706752, 2021). "The loss of proteoglycan especially aggrecan tends to appear in early disc degeneration." (PMID 34307680, 2021). "Since metalloproteinases, particularly members of the ADAMTS and matrix metalloproteinase (MMP) families, are major contributors to aggrecan degradation and loss in disc degeneration, MMP-3, ADAMTS-4 and ADAMTS-5 message levels were also examined, as their suppression is essential for disc repair." (PMID 21787415, 2011). "Furthermore, aggrecan loss is a feature of disc degeneration, and its replacement is essential for repair." (PMID 21787415, 2011). "In turn, production of a proteoglycan, called aggrecan, that makes up the cartilage structure, will drop, and this will accelerate disc degeneration." (PMID 40868398, 2025). "Interleukin-1 (IL-1) induced disc degeneration manifested by increased glycosaminoglycan release in media and reduced aggrecan and collagen II mRNA levels in disc cells." (PMID 40862709, 2025). "Another association was examined between the aggrecan variable number of tandem repeat (VNTR) polymorphism and disc degeneration amongst the Chinese Han in northern China." (PMID 36248118, 2022). "In conclusion aggrecan gene VNTR polymorphism had an association with degeneration of lumbar intervertebral disc, so the shorter VNTR repeats increase the chance of the disc degeneration in this Iranian population." (PMID 35919638, 2022). "In vivo, NPC spheroids generated more functional ECM components, primarily aggrecan (ACAN) and collagen type II (Col2), and markedly promoted NP regeneration in the disc degeneration model induced by partial NP excision." (PMID 35813471, 2022). "Conversely, inhibition of the NF‐κB signalling pathway resulted in an increase in aggrecan by decreasing matrix degradation in a mouse disc degeneration model." (PMID 33734570, 2021). "We found that cells grown in static culture and 0.25L STR exhibited similar doublings, identity, aggrecan production and bioactivity in vivo, measured by increased disc height in rabbit disc degeneration model, as previously seen for Discogenic Cells." (PMID 34384480, 2021). "In disc degeneration, the concentration of aggrecan is reduced due to increased breakdown and reduced synthesis of aggrecan molecules leading to disc dehydration." (PMID 28742099, 2017). "Collagen-II and aggrecan are the main components of nucleus pulposus, and the reduction of collagen-II content is highly correlated with disc degeneration." (PMID 27190710, 2016).
disc degeneration (continued). "SIRT1 treatment significantly reduced aggrecan, Sox9 and collagen type 2 mRNA expression in a dose-dependent manner in all disease classes and disc degeneration grades." (PMID 22152608, 2011). "During disc degeneration the production of both aggrecan and collagen type II is decreased leading to reduced hydration and ability to withstand load." (PMID 19754961, 2009). "Although these catabolic factors were counteracted by even higher and increasing expression levels of their natural endogeneous inhibitors such as TIMP-1, TIMP-2, TIMP-3 and TIMP-4, we recoded declining levels of aggrecan and collagen II with increased severity of disc degeneration." (PMID 39286594, 2024). "The hyalectanases are responsible for aggrecan degradation in disc degeneration." (PMID 35163637, 2022). "Finally, we grow discogenic cells in stirred tank reactors (STRs) and test outcomes in vitro (potency via aggrecan production and identity) and in vivo (rabbit model of disc degeneration)." (PMID 34384480, 2021). "Furthermore, the researchers found that the administration of H2O2 into the cultured disc cells increased the expression of catabolic factors of disc degeneration, as assessed through RT‐PCR analysis, to reduce aggrecan levels." (PMID 33734570, 2021). "Importantly, polymorphisms in ECM genes including ACAN, COL1, COL 2, COL9, COL11, FN, HAPLN1, THBS, CILP, ASPN; and ECM related genes: GDF5, MMP1, MMP2, MMP3, and TIMP have been correlated with human disc degeneration." (PMID 33543030, 2020). "A likely explanation for for these results is a loss of collagen type II and aggrecan, which are essential components of the NP extracellular matrix and molecular targets for the majority of MMP's and ADAMTS's results in ECM breakdown and progression of disc degeneration." (PMID 36248158, 2022). "Thus, findings of the two studies suggest that SNVs of candidate genes in inflammatory and catabolic pathways are responsible for the variation in the severity of disc degeneration while SNVs of ACAN (structural gene) are responsible for the variation in the severity of disc herniation." (PMID 28742099, 2017). "The extracellular matrix (ECM) of the NP is mainly maintained by type II collagen (Col-2) and Aggrecan in a healthy state, and ECM degradation is crucial for disc degeneration." (PMID 37790932, 2023). "Our findings revealed that digoxin treatment inhibited the upregulation of MMP-13 and ADAMTS4/5 induced by TNF-α, leading to restoration of the expression of Col-2 and Aggrecan, indicating its potential role in inhibiting ECM degradation in disc degeneration." (PMID 37790932, 2023). "The reduction of type II collagen, aggrecan, and SOX-9 in NPCs is usually related to a severe disc degeneration." (PMID 33505586, 2021). "We showed in our previous studies with a larger range of patient population (78 patients with disc degeneration grade III, IV and V) higher levels of ADAMTS4 and lower levels of aggrecan in grade IV and V discs." (PMID 28207788, 2017). "Histological examinations and aggrecan, Col1A1, Col2A1 and matrix metalloprotease (MMP)-3 mRNA expression confirmed the disc degeneration, supporting the imaging results." (PMID 26924131, 2016). "Biochemically, disc degeneration is known by decreased expression of ECM, such as aggrecan shifts in the collagen expression and changes in collagen cross-linking indicative of increased matrix turnover." (PMID 25763091, 2015). "Coupled with the accelerated degradation of collagen II and aggrecan, CTGF stimulates to produce collagen I and III at the transcription levels; thereby, interstitial fibers continue to proliferate, accelerating the process of disc degeneration." (PMID 40190527, 2024). "Intermittent injection of PTH (iPTH) effectively attenuates disc degeneration of aged mice by direct signaling through NP cells, specifically improving intervertebral disc height and volume by increasing levels of TGF-β activity, CCN2, and aggrecan." (PMID 30038820, 2018).
disc degeneration (continued). "Therefore, the identification of asporin as a negative regulator of aggrecan and type Π collagen, as well as the elucidation of the mechanisms by which it is induced in human nucleus pulposus cells, may provide potential immune-based anti-disc degeneration therapies by targeting asporin expression." (PMID 28646230, 2017). "Interestingly, our study demonstrated that digoxin treatment activated the ERK1/2 and AKT pathways, leading to increased mRNA expression of Aggrecan and Col-2, suggesting its potential role in promoting ECM anabolism and counteracting the catabolic processes in disc degeneration." (PMID 37790932, 2023). "It is believed that nerve fibers hardly extend into the normal disc without annular rupture or disc degeneration because of the tight collagen network of the uninjured annulus and the presence of disc aggrecan, which has an inhibiting effect on extending nerve fibers." (PMID 25069717, 2014).